IL4 (interleukin 4)
Diseases named in the same sentence as IL4 in open-access papers (continued):
Sharing a sentence is not in itself a finding about the gene and the disease.
asthma (continued). "In recent years, clinical drugs have been developed to improve the symptoms of asthma with potential therapeutic effects on IL-4, IL-5, and IL-13 expression levels." (PMID 32244835, 2020). "In this study, we observed that Tespa1 is associated negatively with the IL-4/STAT6 signaling pathway in the activation of mast cells, thus providing a new intervention target for mast cells in the pathogenesis of asthma." (PMID 33228696, 2020). "Th2 cells and type 2 cytokines, such as IL-4, IL-5, and IL-13, were initially identified as proinflammatory cells and factors in asthma 1-3." (PMID 32549755, 2020). "Overproduction of IL-4 seems to contribute to the pathophysiology of asthma and appears to play an important role in airway remodeling, Th2 cell development, IgE synthesis, and B-cell growth and proliferation." (PMID 32411263, 2019). "A simplistic explanation is that individual blockade of IL-4 or IL-13 is insufficient to inhibit the complex orchestration of allergic inflammation and clinical consequences in severe asthma." (PMID 31866859, 2019). "IL-4 aids in directing naïve CD4+ Th cells towards a Th2 phenotype, while IL-13 enhances airway inflammation and remodeling; dupilumab has dual inhibition of both IL-4 and IL-13 which demonstrates more beneficial effects in asthma therapy." (PMID 31728232, 2019). "Eos asthma is known to be associated with the Th2 pathway and IL4, IL5, and IL13 are involved in “Th2-high” asthma." (PMID 30941157, 2019). "It has since been shown that Th2 cells play a central role in the pathogenesis of asthma by secreting typical Th2 cytokines, such as interleukin (IL)-4, IL-5, and IL-13." (PMID 31216735, 2019). "INF-γ/IL-4 ratio was also increased in sensitized rats treated with ALA which indicated increased Th1/Th2 balance due to ALA treatment in animal model of asthma." (PMID 31156785, 2019). "Although these are very important host factors, several authors have suggested that Th2 cytokine genes such as IL-4, IL-13, and IL-5 contribute to asthma severity." (PMID 31572372, 2019). "Discovered DMRs annotated to genes implicated in allergic asthma, Th2 activation and eosinophilia (EPX, IL4, IL13) and genes previously associated with asthma and IgE in EWAS of blood (ACOT7, SLC25A25)." (PMID 31300640, 2019). "Th2 cells release various proallergic inflammatory cytokines, such as IL-4, IL-5, IL-13, and GM-CSF, which activate basophils and eosinophils and increase mucus secretion in the airway in patients with asthma." (PMID 31284537, 2019). "Generally, few studies have examined the effects of moderate aerobic exercise training on the serum INF-γ/IL-4 ratio (Th1/Th2 balance) in asthma patients." (PMID 32411263, 2019). "There is an obvious reason for the weak efficacy of asthma therapies targeting IL-4 and IL-13 since both cytokines share the same signaling pathway." (PMID 31216735, 2019). "In this murine model of asthma, IL-4 is essential in class switching of immunoglobulins produced by plasma cells and the subsequent development of adaptive TH2 and humoral immunity (production of IgE antibodies to allergens)." (PMID 30736433, 2019). "Prenatal cytokine production (cord-blood concentrations of IL-4, IFN-γ, and tumor necrosis factor) was associated with the development of atopy and asthma at 6 years of age." (PMID 31507589, 2019). "IL-4 VNTR gene polymorphisms have also been linked with immune thrombocytopenic purpura (ITP) and asthma in the current literature." (PMID 31650822, 2019). "Targeting this pathway through the inhibition of cytokines (IL-4 and IL-13) and their receptors, JAKs or STATs, has been shown to have a therapeutic effect on asthma pathology." (PMID 31284537, 2019). "IL-4, IL-5, and IL-13, while important for promoting the clearance of parasites, can promote a disease state when improperly expressed, such as with asthma and allergy, by activating immune cells involved in these pathologies." (PMID 30630412, 2019).
asthma (continued). "In the case of equine asthma, this leads to an immune shift from a Th2 to a Th1 reaction, suppression of IL-4, increase in IL-10 and IFN-gamma, and a cytological reduction in neutrophils in respiratory secretions." (PMID 31316303, 2019). "Significant increases in IL-4, IgE, PLA2 and TP levels, significant decrease in IFN-γ/IL-4 ratio, increased all pathological changes were seen in a rat model of asthma compared to control group." (PMID 31801507, 2019). "Type 2 cytokines such as IL-4, IL-5, and IL-13 play a critical role in mucous cell metaplasia and mucus hypersecretion during asthma." (PMID 30654796, 2019). "Recently, therapies targeting IL-4, IL-5, and IL-13 have shown potential efficacy for treating asthma." (PMID 31114590, 2019). "We also found that NIP45 deficiency led to a significant decrease of the Th2 cytokines IL-4, IL-5 and IL-13, which are the principle components in the onset of asthma." (PMID 31666531, 2019). "Development of antagonistic antibody (Ab) against interleukin-4 receptor alpha (IL-4Rα) subunit of IL-4/IL-13 receptors is a promising therapeutic strategy for T helper 2 (TH2)-mediated allergic diseases such as asthma and atopic dermatitis." (PMID 31123339, 2019). "Drugs targeting the T2 cytokines IL-4 and IL-13 also appear to play a role in reducing exacerbations in patients with severe asthma." (PMID 31395050, 2019). "The IL-4 cytokine has multiple and important participation in asthma, such as modulation in growth, differentiation and degranulation of mast cells, regulation of IgE synthesis by B lymphocytes, stimulation of mucus producing cells, and inhibition of TH1." (PMID 31015955, 2019). "In particular, Th2 cytokines including IL-4, -5, and -13 play critical roles in the development and maintenance of asthma." (PMID 31823765, 2019). "Patients with T2-high asthma have eosinophilia and other signs of type 2 inflammation including high levels of IL-4 and IL-13." (PMID 31866859, 2019). "To understand how miR-146a expression is regulated in the airway epithelial cells, we stimulated primary cultured HBECs from healthy donors with cytokines associated with asthma pathogenesis, including IFN-γ, TNF-α, IL-17A, IL-22 and IL-4." (PMID 31798831, 2019). "Currently, dupilumab is the only available biologic drug targeting both IL-4 and IL-13, approved to treat patients with moderate-to-severe asthma and airway or peripheral eosinophilia." (PMID 31355170, 2019). "The importance of type 2 immune responses, characterized by the production of interleukin-4 (IL-4), IL-5, and IL-13, has received much attention in the pathogenesis of asthma." (PMID 31114590, 2019). "Dupilmab, however, has shown efficacy in treating a wide array of Th2 dependent diseases including AD and asthma, likely through modulation of IL-4 and IL-13’s interaction with immune cells." (PMID 31261951, 2019). "Increased polarization and activation of M2 macrophages, which was induced by interleukin (IL)-4 and IL-13, are found in asthma and are suggested to be involved in asthma pathogenesis." (PMID 31547356, 2019). "The anti-IL-4Rα antibody is directed against IL-4Rα and blocks the IL-4 and IL-13 pathways; this asthma treatment is under development." (PMID 31284537, 2019). "Increased Th2 responses are clearly involved in the onset of asthma and other atopic conditions because IL-4 and IL-13 are required for IgE synthesis and IL-5 is necessary for the recruitment of eosinophils." (PMID 31195744, 2019). "Corticosteroid treatment in asthma, is associated in the downregulation of BAL cells expressing mRNA for IL-4 and IL-5 and in the upregulation of cells expressing mRNA for IFN-γ." (PMID 31001262, 2019). "Testing and analysis for total IgE, aeroallergen-specific IgE antibodies, serum cytokines IL-4, IL-13, IL-10, and IFN-γ levels, and total peripheral eosinophilic index were used as immunological biomarkers known to be associated with asthma." (PMID 31336954, 2019).
asthma (continued). "Progesterone treatment on ovariectomized asthma model mice increased serum IgE levels and IL-4 production in bronchoalveolar lavage cells, indicating the contribution of progesterone to the elicitation of allergic diseases." (PMID 31547021, 2019). "More recently biologic therapies that target T2 pathways including IL-4, IL-13, and IL-5 have been shown to be effective in patients with asthma and nasal polyps." (PMID 31294006, 2019). "We previously reported higher IL-19 expression in asthma patients and that patients with high IL-19 expression also have high IL-4 and IL-13 expression." (PMID 31114590, 2019). "Considering the individual relevance of IL-4 and IL-13 in the pathogenesis of asthma, these results are surprising and intriguing." (PMID 31866859, 2019). "As one of the important factors that regulate asthma severity, IL-6 induces IL-4 up-regulation and stimulates Th17 cell differentiation." (PMID 31790411, 2019). "The serum levels of IL-4 in control, allergic rhinitis, asthma and complication groups were (5.23±2.78), (82.17±32.45), (69.42±36.19) and (80.65±33.01) ng/L, respectively." (PMID 30344593, 2018). "M2 macrophages are characterized by the increased expression of IL-4 and IL-13, which are very crucial cytokines in asthma pathogenesis." (PMID 29316647, 2018). "Regarding to importance of the relationship between cytokine imbalance (Th1/Th2) in both atopy and asthma expression we selected IL4 as a Th2 profile." (PMID 29743896, 2018). "Th1 cytokines, such as IFN-γ, inhibit allergen-induced eosinophil recruitment and IgE release via downregulating GATA-3, IL-4, and IL-5 expression in the lung tissues of asthma model." (PMID 29991953, 2018). "As a Th2-driven inflammatory response, asthma is characterized by increase in the levels of IL-4, IL-5, IL-13, and GM-CSF along with an increase in the level of TNF-α and TGF-β in BALF and serum, which primarily act as pro-inflammatory cytokines." (PMID 30619345, 2018). "Serum IL-4, IL-5, IL-10, adhesion molecules and sE-selectin are all involved in the pathogenesis of allergic rhinitis and asthma, which can be used to evaluate the degrees of respiratory allergic diseases." (PMID 30344593, 2018). "FA aggravates asthma, at least in part by increasing the T helper-2 dominant response, which is related to levels of the cytokine mediators of asthma (IL-4, IL-5, IL-9, and IL-13)." (PMID 29780828, 2018). "A role of mTOR in the onset of asthma has been proposed, and both the mTOR pathway and NF-kB are activated following TNFα/ IL-4 mediated stimulation in the bronchial epithelial cell line BEAS-2B." (PMID 29320511, 2018). "The serum levels of IL-4 in patients with moderate (1.66±0.06 pg/mL) and severe asthma (1.66 ± 0.10 pg/mL) were significantly higher than that of the healthy controls (1.42 ± 0.04 pg/mL; P <0.004 and P <0.02, respectively)." (PMID 30116273, 2018). "Many of the methylation sites we identified have been associated with asthma including ADAM19, EPX, IL4, IL5RA, and PRG2." (PMID 29692868, 2018). "The central role of IL-4 in the initiation of asthma makes cytokines an interesting target for therapeutic interventions." (PMID 31826038, 2018). "The location of the PCDH 1 is in 5q 31-33 chromosome which is the harboring zone for several genes like Interleukin-4 (IL-4), Interleukin-5 (IL-5), Interleukin-13 (IL-13), the candidate genes for asthma and allergy traits." (PMID 30510870, 2018). "The expression of serum IL-1β, IL-4, and IL-17F were all significantly increased in the asthma model animals when compared with levels in mice from the PBS + PBS group (P < 0.05, P < 0.01, and P < 0.001, respectively)." (PMID 30089474, 2018). "Pedroza showed that pediatric asthmatic patients undergoing exacerbations of asthma displayed increased numbers of iNKT cells in the blood that also produced less IFN-γ and more IL-4 than children with stable asthma or in healthy control children." (PMID 30210497, 2018).
asthma (continued). "Immune and epithelial cells of the lung can respond to inhaled substances by the release of central mediators of asthma, such as IL-4 and IL-13, as well as inflammatory mediators, such as IL-1β, and immune cell attracting proteins, such as Mcp-1." (PMID 29614747, 2018). "It has also been demonstrated that p38 MAPK pathway regulated the expression of IL-4 and IL-5 at the levels of mRNA and protein, which played a crucial role in the pathogenesis of asthma." (PMID 29554934, 2018). "In a cohort of 223 HIV infected persons, doctor diagnosed asthma appeared to be more common in participants with high sputum interleukin 4 (IL-4) (27% with asthma if high IL-4 vs.10.5% with asthma if low IL-4, p = 0.02)." (PMID 30241519, 2018). "Specifically, we identified multiple methylation loci in genes previously associated with asthma (ADAM19, EPX, IL4, IL5RA, and PRG2) from genome-wide and epigenome-wide association studies." (PMID 29692868, 2018). "The asthma group showed a statistically significant upregulation in gene expression of IL-4 and IL-5, evaluated using the homogenate of lung parenchyma)." (PMID 29772010, 2018). "In our study, the concentrations of IL-4 had been increased during acute asthma exacerbation, in comparison with that of healthy controls." (PMID 30210646, 2018). "The interbalance of IFN-γ and IL-4 secreted by Th1 and Th2 lymphocyte subgroups, respectively, contributes largely to the progression of asthma." (PMID 30186353, 2018). "The serum levels of TGF-β and IL-4 were significantly higher in patients with asthma than the healthy controls (321.70 ± 35.12 vs. 226.69 ± 17.81 pg/mL, P <0.03 and 1.66 ± 0.05 vs 1.42 ± 0.04 pg/mL, P <0.002; respectively)." (PMID 30116273, 2018). "PHF also significantly suppressed pulmonary eosinophilia and asthma-related cytokines IL-4 and IL-33 in bronchoalveolar lavage (BAL) fluid." (PMID 30373169, 2018). "Inflammatory cytokines like interleukin-4 (IL-4), IL-5, and IL-13 are also increased and altered along with asthma exacerbation." (PMID 30170608, 2018). "The adoptive transfer of IL-4- and IL-13-producing iNKT cells restored the asthma severity, demonstrating that iNKT cells favored allergic asthma symptoms through the production of these cytokines." (PMID 30105031, 2018). "As a downstream molecule of IL-4 and IL-13, it has been proposed as an important biomarker of the Th2-high eosinophilic phenotype of asthma." (PMID 29580282, 2018). "Asthma-induced Brucella susceptibility appears to be dependent on CD4+ T cells, the IL-4/STAT6 signaling pathway and IL-10, and is maintained in IL-12- and IFN-γR-deficient mice." (PMID 30147700, 2018). "Support for this mechanism came from studies using an AP-1 decoy molecule, which was used to block IL-4 and IL-13 production, and ameliorate disease symptoms in a model of asthma." (PMID 30459773, 2018). "BALB/c mice were challenged with OVA for the asthma model, which was validated by the changed levels of IL-4, IFN-γ, and IgE." (PMID 30186353, 2018). "Dupilumab that blocks IL4Rα, a subunit of both the IL-4 and IL-13 receptors, interferes with the action of both these cytokines and to date has had success in treating asthma and atopic dermatitis." (PMID 29910811, 2018). "The current study results also demonstrated that in both patients with moderate and severe asthma, serum levels of IL-4 and GTAT3 expression were higher than those of the healthy individuals." (PMID 30116273, 2018). "IL-4 increased in blood and bronchoalveolar lavage in patients with allergic asthma, particularly high in patients with severe asthma which was resistant to corticosteroids." (PMID 30210646, 2018). "Dupilumab, a targeted therapy against IL-4R-alpha that modulates the IL-4/IL-13 pathway, improved asthma control and lung function in asthmatic patients with sputum eosinophilia (≥3%) or blood eosinophilia (≥300/μL)." (PMID 30598830, 2018).
asthma (continued). "Several of these methylation loci were previously associated with asthma (ADAM19, EPX, IL4, IL5RA, and PRG2)." (PMID 29692868, 2018). "For diagnosing asthma severity, the AUC of the miR-1 expression level was the highest (AUC = 0.977, P < 0.05), followed by the IL-4 level (AUC = 0.963, P < 0.05) and the IFN-γ level (AUC = 0.885, P < 0.05)." (PMID 30046607, 2018). "Mice deficient for IL-4, IL-13, or STAT6 develop attenuation of certain features of asthma, including eosinophil recruitment and airway hyperresponsiveness." (PMID 30147700, 2018). "Th1 cells exert a protective effect on asthma through releasing IFN-γ and IL-2, while Th2 cells mainly secrete IL-4, IL-5, and IL-13, and then promote the development of asthma." (PMID 30089474, 2018). "The “Th2-dependent” inflammatory subtype of asthma or CRS is mediated to a large extent by IL-4, IL-5, and IL-13 cytokines." (PMID 29707206, 2018). "Recent studies also report positive findings on the efficacy of new therapies targeting cytokines interleukin IL-13 and IL-4 in asthma and atopic dermatitis." (PMID 29771307, 2018). "Th2 cells produce interleukin 4 (IL-4), IL-5, IL-9, IL-10, and IL-13, which are important for pathological implications in asthma and allergic diseases." (PMID 30314368, 2018). "In asthma, Th2-related cytokines such as IL-4, IL-5, and IL-13 significantly increase; the development of antibodies against Th2-related cytokines is an active field of research." (PMID 29151835, 2017). "A number of analyses using asthma model mice have established the significance of IL-4 and/or IL-13, particularly the latter, in the pathogenesis of asthma." (PMID 29359006, 2017). "Compared to moderate asthma, IL-4 expression was decreased and IL-17A expression was increased in severe asthma." (PMID 28808358, 2017). "IL-13 is closely related to IL-4, which binds to IL-4R receptors and is also expressed by Th2 cells from asthma patients." (PMID 28570692, 2017). "Moreover, IL-4 can activate B cells to secrete IgE and bind to mast cells; this binding activates the complex of allergic responsive IgE and mast cells, and they release leukotrienes and histamine; these factors cause acute allergic and inflammatory reactions in patients with asthma." (PMID 28243240, 2017). "Similar to asthma, AD, and EoE, it is believed that IL-4 and IL-13 play important roles in the pathophysiology of ECRSwNP." (PMID 29034234, 2017). "The Th2-derived cytokines, IL-4, IL-5, IL-9, and IL-13 mRNA expression was also markedly increased in the patients with severe asthma patients with CRS." (PMID 28199345, 2017). "Enriched pathways included those also triggered by other atopic conditions, and particularly asthma (i.e. IL-4 immune signaling), also evidenced by the efficacy of specific Th2 targeting-strategies in both AD and asthma." (PMID 28821884, 2017). "CpG promoter loci of asthma genes (i.e., interleukin 4 (IL4), interferon gamma (IFNγ), inducible nitric oxide synthase (NOS2A), arginase 2 (ARG2)) were pyrosequenced and lung function was assessed." (PMID 28424066, 2017). "IL-12p40 (p = 0.005), IL-13 (p = 0.04), IL-1β (p = 0.02), and IL-4 (p = 0.03) were increased in those with Easy-to-Control asthma." (PMID 28686637, 2017). "This study is the first investigation in Iraq dealing with genotyping of IL-4 −590 (C>T) gene, especially in Iraqi patients with asthma." (PMID 28386156, 2017). "Th2 cytokines such as IL-4, -5, and -13 are considered markers of asthma, and IL-4 is the main cytokine involved in the pathogenesis of allergic disorders, including stimulation of mucus-producing cells and fibroblasts." (PMID 28570692, 2017). "CD4+ T helper cells play an important role in the pathogenesis of asthma by secreting IL-4, IL-5 and IL-1326." (PMID 28240301, 2017). "In that regard, recent asthma treatments have been focusing on blocking Type 2 cytokines, notably IL-4, IL-5, and IL-13." (PMID 28848734, 2017).